DCAF4L1 (DDB1 and CUL4 associated factor 4 like 1)
Synonyms: WDR21B
Tractability: No criterion of Open Targets' tractability assessment is met for any kind of drug.
Gene: Protein-coding gene on chromosome 4 (41,981,756 to 41,986,465, forward strand). Ensembl gene ENSG00000182308.
Subcellular location: Cytoplasm
Subcellular location (Human Protein Atlas): Cytosol; Nucleoli
Gene Ontology:
Cellular component: cytoplasm; cytosol; Cul4-RING E3 ubiquitin ligase complex
Genetic constraint (gnomAD): Loss-of-function variants: 4 observed, 31.08 expected, observed/expected ratio (o/e) 0.13, 90% interval 0.062 to 0.29. The upper end of that interval is the gene's LOEUF score, 0.29, which puts it in group 1 of 6, group 1 being the genes least tolerant of losing a copy. Missense variants: 331 observed, 535.15 expected, observed/expected ratio (o/e) 0.62, 90% interval 0.56 to 0.68. Synonymous variants: 252 observed, 226.2 expected, observed/expected ratio (o/e) 1.11, 90% interval 1 to 1.24.
Homologues: Orthologues: macaque DCAF4L1 (98% identical). Paralogues in human: DCAF4 (77% identical), DCAF4L2 (74% identical), SNRNP40 (14% identical), WDR7 (14% identical), AHI1 (14% identical), WDR27 (13% identical), MAPKBP1 (13% identical), POC1A (13% identical), WDR5B (13% identical), WDR17 (12% identical), WDR5 (12% identical), POC1B (12% identical), and 14 more.
Diseases named in the same sentence as DCAF4L1 in open-access papers:
DCAF4L1 is named in the same sentence as 4 diseases in open-access papers, as found by Europe PMC text mining. Sharing a sentence is not in itself a finding about the gene and the disease. The quoted sentences say what the papers report.
germ cell tumor (1 paper, 2021). A benign or malignant, gonadal or extragonadal neoplasm that originates from germ cells. "DCAF4L1 shows significant differential expression in 14 cancers versus normal controls and is detected in ovarian and testicular germ cell tumors." (PMID 33426787, 2021).
DCAF4L1 also shares sentences with these, for which no sentence is quoted: cancer (2 papers); bladder cancer (1); kidney cancer (1).